LHFPL2 (LHFPL tetraspan subfamily member 2)
Description:
Plays a role in female and male fertility. Involved in distal reproductive tract development.
Synonyms: KIAA0206
Tractability: Antibody: its Gene Ontology location is reachable by antibodies, with high confidence; UniProt predicts a signal peptide or a membrane-spanning region; the Human Protein Atlas places it where antibodies can reach. PROTAC: ubiquitination databases record sites on it.
Gene: Protein-coding gene on chromosome 5 (78,485,215 to 78,770,021, reverse strand). Ensembl gene ENSG00000145685.
Subcellular location: Membrane
Subcellular location (Human Protein Atlas): Plasma membrane; Nuclear bodies; Vesicles
Pathways (Reactome):
Hemostasis: Platelet degranulation
Gene Ontology:
Molecular function: protein binding
Biological process: development of primary female sexual characteristics; development of primary male sexual characteristics; positive regulation of fertilization
Cellular component: membrane; plasma membrane; platelet alpha granule membrane
Genetic constraint (gnomAD): Loss-of-function variants: 7 observed, 17.65 expected, observed/expected ratio (o/e) 0.4, 90% interval 0.22 to 0.75. The upper end of that interval is the gene's LOEUF score, 0.75, which puts it in group 3 of 6, group 1 being the genes least tolerant of losing a copy. Missense variants: 241 observed, 311.43 expected, observed/expected ratio (o/e) 0.77, 90% interval 0.7 to 0.86. Synonymous variants: 134 observed, 122.39 expected, observed/expected ratio (o/e) 1.09, 90% interval 0.95 to 1.26.
Homologues: Orthologues: chimpanzee LHFPL2 (100% identical), macaque LHFPL2 (99% identical), pig LHFPL2 (94% identical), dog LHFPL2 (93% identical), guinea pig LHFPL2 (93% identical), rabbit LHFPL2 (90% identical), mouse Lhfpl2 (84% identical), tropical clawed frog lhfpl2 (84% identical), rat Lhfpl2 (83% identical), zebrafish lhfpl2a (72% identical), zebrafish lhfpl2b (70% identical), Drosophila melanogaster CG3770 (31% identical). Paralogues in human: LHFPL1 (25% identical), LHFPL6 (25% identical), LHFPL4 (23% identical), LHFPL3 (22% identical), LHFPL5 (18% identical), LHFPL7 (17% identical).
Diseases named in the same sentence as LHFPL2 in open-access papers:
LHFPL2 is named in the same sentence as 22 diseases in open-access papers, as found by Europe PMC text mining. Sharing a sentence is not in itself a finding about the gene and the disease. The quoted sentences say what the papers report.
lipoma (4 papers, 2022 to 2023). A benign, usually painless, well-circumscribed lipomatous tumor composed of adipose tissue. "As shown in the Venn diagram, the intersection showed two differentially expressed mRNAs: MACC1 (metastasis-associated in colon cancer-1) and LHFPL2 (lipoma HMGIC fusion partner-like 2)." (PMID 35279159, 2022). "The family of genes known as the lipoma HMGIC fusion partner (LHFP) includes the LHFPL tetraspan subfamily member 2 (LHFPL2)." (PMID 37589508, 2023). "LHFPL tetraspan subfamily member 2 (LHFPL2) is a member of the lipoma HMGIC fusion partner (LHFP) gene family." (PMID 35847972, 2022). "Fewer reports are available on lipoma HMGIC fusion partner-like 2 protein(LHFPL2)." (PMID 36325528, 2022).
coronary artery disease (2 papers, 2021 to 2022). "LHFPL2 has been implicated in diverse physiological functions, including long-term proliferation of leukemic cells, coronary heart disease and infertility." (PMID 35619132, 2022).
depression (2 papers, 2022). "No studies have reported a direct association of S100A12, TIGIT, SERPINB2, GRB10, and LHFPL2 with depression." (PMID 36325528, 2022). "ROC analysis based on both GSE98793 and GSE76826 datasets suggested that S100A12, TIGIT, SERPINB2, GRB10, and LHFPL2 in the peripheral serum have the potential to act as diagnostic biomarkers for depression." (PMID 36325528, 2022). "The genes S100A12, TIGIT, SERPINB2, GRB10, and LHFPL2 in peripheral serum are viable diagnostic biomarkers for depression." (PMID 36325528, 2022). "S100A12, TIGIT, SERPINB2, GRB10, and LHFPL2 identified as potential diagnostic biomarkers in peripheral blood of patients with depression using three machine learning algorithms." (PMID 36325528, 2022). "Subsequently, S100A12, TIGIT, SERPINB2, GRB10, and LHFPL2 in peripheral blood were identified as Potential diagnostic biomarkers in peripheral blood for depression by SVM–REF, Random forest, and LASSO algorithms." (PMID 36325528, 2022). "Based on the results of the ROC (validation set AUC value > 0.7) analysis in the current study, S100A12, TIGIT, SERPINB2, GRB10, and LHFPL2 may possess potential as diagnostic biomarkers of depression." (PMID 36325528, 2022). "Among them, the relevance scores of S100A12, TIGIT, SERPINB2, GRB10, and LHFPL2 with depression were 4.356, 4.232, 3.064, 1.516, and 0.698, respectively." (PMID 36325528, 2022). "Subsequently, the genes S100A12, SERPINB2, TIGIT, GRB10, and LHFPL2 in peripheral serum were identified as depression biomarkers by using machine learning algorithms." (PMID 36325528, 2022). "We further investigated the role of S100A12, TIGIT, SERPINB2, GRB10, and LHFPL2 in depression and observed their expression profiles in patients." (PMID 36325528, 2022). "The expression level of 100A12, SERPINB2, GRB10, and LHFPL2 was higher in the depression group, whereas TIGIT showed a high expression profile in the normal control group." (PMID 36325528, 2022). "Finally, the results from the three algorithms were combined, yielding S100A12, TIGIT, SERPINB2, GRB10, and LHFPL2 in peripheral blood as depression-related potential biomarkers." (PMID 36325528, 2022).
infertile (2 papers, 2016 to 2022). "A spontaneous point mutation of Lhfpl2 (LHFPL2G102E) leads to infertility in 100% female mice, which have normal ovarian development, ovulation, uterine development, and uterine response to exogenous estrogen stimulation, but abnormal upper longitudinal vaginal septum and lower vaginal agenesis." (PMID 26964900, 2016).
Parkinson disease (2 papers, 2021 to 2023). A progressive degenerative disorder of the central nervous system characterized by loss of dopamine producing neurons in the substantia nigra and the presence of Lewy bodies in the substantia nigra and locus coeruleus. "Among disease-associated genes were those associated with autism (CSDE1) and Parkinson’s disease (LHFPL2)." (PMID 37106565, 2023). "Interestingly, regarding Parkinson’s disease, another neurodegenerative disorder, genetic variants located in LHFPL2 have been associated with accelerated onset of the disease by 8 to 12 years." (PMID 34404460, 2021).
anaplastic astrocytoma (1 paper, 2024). "A tumour with the LHFPL2::NTRK2 fusion in the left temporal lobe of patient #5 (27 y/F) had features of anaplastic astrocytoma with neuropil-like islands, on the basis of the diagnostic criteria of the WHO2016 classification." (PMID 39014476, 2024).
Azoospermia (1 paper, 2016). Absence of any measurable level of sperm,whereby spermatozoa cannot be observed even after centrifugation of the semen pellet. "It is interesting to investigate if LHFPL2 mutations are associated with longitudinal vaginal septum, vaginal agenesis, or obstructive azoospermia in humans." (PMID 26964900, 2016).
Hodgkins lymphoma (1 paper, 2021). A heterogeneous group of malignant lymphoid neoplasms of B-cell origin characterized histologically by the presence of Hodgkin and Reed-Sternberg (HRS) cells in the vast majority of cases. "CD79 has been extensively studied in hematological tumors and has been reported to be more positive in elderly Hodgkin’s lymphoma patients with poor prognosis; however, IGLL5 and LHFPL2 are less often studied in tumors and their functions remain unknown." (PMID 34900411, 2021).
hypospadias (1 paper, 2025). Hypospadias is the displacement of the urethral meatus on the ventrum of the penis. "Although the LHFP gene itself has not been previously linked to hypospadias, functional studies of related gene family members such as LHFPL2 have reported causes of hypospadias-like phenotypes in mice and suggested a mechanistic role of the encoded protein in genital development." (PMID 41300791, 2025). "Although LHFP has not previously been linked to hypospadias, functional studies on related genes (LHFPL2) suggest a role in genital development." (PMID 41300791, 2025).
mastitis (1 paper, 2023). Inflammation of breast tissue during lactation or postpartum due to an obstructed duct or infection. "For the trait of mastitis, 3 significant SNPs were enriched near LHFPL2." (PMID 37592228, 2023).
melanoma (1 paper, 2025). A malignant, usually aggressive tumor composed of atypical, neoplastic melanocytes. "In human melanoma, SerpinE2 expression has previously been associated with high invasive potential of slow-cycling cells, and LHFPL2 expression was associated with mTORC1 signaling, which promotes mesenchymal-epithelial transition in cancer." (PMID 40950124, 2025).
Salmonella Infections (1 paper, 2021). Infections with bacteria of the genus SALMONELLA. "Many of these genes (e.g. Lhfpl2, Bhlhe41, Hyal1, and Tbc1d2) have previously been reported as differentially expressed in M1 vs. M2 macrophages and their downregulation likely represents M1 polarization that occurs following Salmonella infection." (PMID 34305890, 2021).
sarcoidosis (1 paper, 2022). Sarcoidosis is a multisystemic disorder of unknown cause characterized by the formation of immune granulomas in involved organs. "In addition, we found that LRRN3, IFI44, LHFPL2, RTP4, and EPHX2 were all involved in diagnosing sarcoidosis, which might shed light on the mechanisms of sarcoidosis and provide potential biomarkers for diagnosis." (PMID 36405616, 2022).
tumor (6 papers, 2021 to 2024). "We comprehensively evaluated the expression of LHFPL2 and its relationship with clinical features, tumor prognosis, immune infiltration, and mutations." (PMID 38928412, 2024). "Our analysis elaborately delineates the immune characteristics of LHFPL2 in the tumor microenvironment and its positive correlation with macrophage M2 polarization, providing new insights into tumor immunotherapy." (PMID 38928412, 2024). "For each tumor sample, a prognostic risk score was computed employing the equation below: prognostic risk score = PAG1 expression × 0.2399877 + LHFPL2 expression × 0.2969381 + FABP5 expression × 0.2441960 (TCGA)." (PMID 37589508, 2023). "Previous literature has shown that LHFPL2 was involved in the tumor microenvironment-related signature." (PMID 37589508, 2023). "Moreover, LHFPL2 showed specific expression in macrophages, with the high-expression subgroup exhibiting higher M2 polarization, hypoxia, immune evasion, and angiogenesis scores, promoting tumor progression." (PMID 38928412, 2024). "Among that, the protein expression of IGF2BP3, B2M, CD36, CDKN1A, ANKRD33B, and LHFPL2 were up-regulated; However, the protein expression of APP and CTDSPL was low in both normal and tumor tissues." (PMID 39470474, 2024). "We hypothesized that CXCL13 expressed in T cells and CD79A and IGLL5 expressed in B cells could affect the expression of LHFPL2 gene through the CD45 signaling pathway, acting on macrophages, thus jointly playing a role in tumor regulation." (PMID 34900411, 2021).
cancer (3 papers, 2023 to 2025). A tumor composed of atypical neoplastic, often pleomorphic cells that invade other tissues. "Additionally, we further assessed the correlation between LHFPL2 and macrophage M2 polarization using single-cell data and explored its potential as a cancer therapeutic target through molecular docking." (PMID 38928412, 2024).
immune diseases (1 paper, 2022). "So far, we have not found any studies on ECRP (ribonuclease A family member 2C, pseudogene) and LHFPL2 (LHFPL tetraspan subfamily member 2) in inflammatory or immune diseases." (PMID 35045818, 2022).
LHFPL2 also shares sentences with these, for which no sentence is quoted: autism (1 paper); bipolar disorder (1); colon cancer (1); memory impairment (1); multiple myeloma (1); renal cell carcinoma (1).